RN7SL65P (RNA, 7SL, cytoplasmic 65, pseudogene)
Gene: Miscellaneous RNA gene on chromosome 2 (174,240,143 to 174,240,457, reverse strand). Ensembl gene ENSG00000243770.
Homologues: Orthologues: chimpanzee Metazoa_SRP (99% identical). Paralogues in human: RN7SL2 (73% identical), RN7SL1 (73% identical), RN7SL3 (73% identical), RN7SL300P (72% identical), RN7SL479P (71% identical), RN7SL113P (70% identical), RN7SL329P (70% identical), RN7SL712P (70% identical), RN7SL823P (70% identical), RN7SL145P (70% identical), RN7SL220P (70% identical), RN7SL45P (70% identical), and 699 more.